TRBJ1-3 (T cell receptor beta joining 1-3)
Description:
J region of the variable domain of T cell receptor (TR) beta chain that participates in the antigen recognition. Alpha-beta T cell receptors are antigen specific receptors which are essential to the immune response and are present on the cell surface of T lymphocytes. Recognize peptide-major histocompatibility (MH) (pMH) complexes that are displayed by antigen presenting cells (APC), a prerequisite for efficient T cell adaptive immunity against pathogens. Binding of alpha-beta TR to pMH complex initiates TR-CD3 clustering on the cell surface and intracellular activation of LCK that phosphorylates the ITAM motifs of CD3G, CD3D, CD3E and CD247 enabling the recruitment of ZAP70. In turn ZAP70 phosphorylates LAT, which recruits numerous signaling molecules to form the LAT signalosome. The LAT signalosome propagates signal branching to three major signaling pathways, the calcium, the mitogen-activated protein kinase (MAPK) kinase and the nuclear factor NF-kappa-B (NF-kB) pathways, leading to the mobilization of transcription factors that are critical for gene expression and essential for T cell growth and differentiation. The T cell repertoire is generated in the thymus, by V-(D)-J rearrangement. This repertoire is then shaped by intrathymic selection events to generate a peripheral T cell pool of self-MH restricted, non-autoaggressive T cells. Post-thymic interaction of alpha-beta TR with the pMH complexes shapes TR structural and functional avidity.
Synonyms: TRBJ13; TCRBJ1S3
Gene: T-cell receptor joining (J) gene on chromosome 7 (142,787,630 to 142,787,679, forward strand). Ensembl gene ENSG00000282133.
Subcellular location: Cell membrane
Gene Ontology:
Cellular component: plasma membrane